PSAT1 (phosphoserine aminotransferase 1)
Diseases named in the same sentence as PSAT1 in open-access papers (continued):
Sharing a sentence is not in itself a finding about the gene and the disease.
cancer (continued). "In our study, the prognostic value of PSAT1 in pan-cancer was confirmed." (PMID 36105075, 2022). "PSAT1 also contributes to the modulation of cancer progression." (PMID 33526036, 2021). "The chosen therapeutic strategy was based on the glutamine processing pathway in LUAD cells; wherein, we probed the ability of chemical inhibitors against glutaminase (CB‐839) and Psat1 (AOA) to modulate cancer cell growth by restricting the supply of α‐KG to the Krebs cycle." (PMID 31036704, 2019). "Many cancer cells express high levels of phosphoserine aminotransferase 1 (PSAT1)." (PMID 28546457, 2017). "Finally, an in-depth analysis of these data could provide further insights into the molecular mechanisms by which PSAT1 influences metabolic and immune pathways in cancer." (PMID 39186541, 2024). "In summary, PSAT1 may provide a more effective therapeutic strategy for cancer treatment." (PMID 37147729, 2023). "More and more evidence showed that PSAT1 may be a biomarker of many cancers as an oncogene." (PMID 36105075, 2022). "Therefore, PSAT1 is also an important substance in the metabolic pathway of cancer cells." (PMID 36105075, 2022). "In certain cancer types, PSAT1 may contribute to the tumor initiation process, but this is unclear." (PMID 36105075, 2022). "Additionally, we examined whether alterations of PSAT1 genes affect different types of cancer patient’s prognosis." (PMID 36105075, 2022). "Moreover, PSAT1 could be regarded as a prognostic marker in cancer, as PSAT1 overexpression could indicate a poor prognostic outcome." (PMID 34405023, 2021). "Critically, PHGDH, PSAT1, PSPH, SLC1A4, SLC1A5 and SLC38A2 show robust co‐expression patterns in both TCGA tumour samples and CCLE cancer cell lines, suggesting coregulated functionality." (PMID 40660426, 2025). "Data from the human Cancer Cell Line Encyclopedia (CCLE) demonstrated differential expression of these genes across cell lines, with high expression of PHGDH, PSAT1, SLC1A5 and SLC38A2, and low expression of SLC38A4 and SLC7A10." (PMID 40660426, 2025). "Proteins, including TOP2A, BPI, PSAT1, ANLN, and TFRC, were upregulated in five of the six cancer types." (PMID 41049442, 2025). "This pathway consists of three sequential enzymes: phosphoserine aminotransferase 1 (PSAT1), phosphoserine phosphatase (PSPH), and PHGDH, the rate‐limiting enzyme extensively studied as a cancer therapy target." (PMID 40552664, 2025). "In metabolically active cancer cells these processes are often dysregulated through oncogenic activity by enzymes such as Phosphoglycerate Dehydrogenase (PHGDH), Phosphoserine Aminotransferase 1 (PSAT-1) and Phosphoserine Phosphatase (PSPH)." (PMID 38702616, 2024). "Some novel therapeutic agents targeting serine metabolic pathways (e.g., PHGDH, PSAT1, and PSPH) in cancer seem to have great potential." (PMID 37187454, 2023). "Histone methyltransferase G9A increases PSAT1 expression by increasing PSAT1 H3K9me1 levels, which activates the SSP and provides α-KG that enters the TCA cycle, thereby sustaining cancer cell proliferation." (PMID 36755301, 2023). "To comprehensively understand these four lncRNAs (LINC01224, CASC9, LINC00346, and TRPM2-AS) and seven target mRNAs (CCNF, PKMYT1, GCH1, TK1, PSAT1, ADAM33, and DDX11), we performed genome instability, immune, cancer stemness, and drug sensitivity analysis." (PMID 34368141, 2021). "The genes with CNV amplifications exhibited a significantly higher expression in cancer tissues than in normal controls (e.g., HK3 and ENO2), while the genes with CNV deletions exhibited significantly lower expression (e.g., ALDOB and PSAT1)." (PMID 33564363, 2021). "A study has found that the expression of PSAT1, which is an enzyme that catalyzes the second step of the SSP, is related to cell proliferation and cancer development." (PMID 34405023, 2021).
cancer (continued). "The mechanism involving lncRNA MEG8, miR-15a/b-5p, and PSAT1 enriches the understanding of lncRNA MEG8, benefiting the future investigation of lncRNA MEG8 in other cancers." (PMID 33526036, 2021). "Although PHGDH, PSAT1 and PSPH have been identified as prognostic biomarkers of a variety of cancers, including GBMs, if they can serve as potential biomarkers of LGGs has not been extensively studied before." (PMID 31861486, 2019). "The authors demonstrated that deprivation of glucose or glutamine, two major nutrition sources for cancer cells, led to the enhanced c-Myc expression, which in turn activated the expression of three key enzymes of serine synthesis, PHGDH, PSAT1 and PSPH." (PMID 28177894, 2017). "The expression of PHGDH (p < 0.001), PSAT1 (p = 0.001), PSPH (p = 0.008), tumoral SHMT1 (p < 0.001), and stromal SHMT1 (p < 0.001) was different according to cancer subtype." (PMID 27277113, 2016). "We identified a robust upregulation of GLUT1 (SLC2A1), a key rate-limiting factor in the transport of glucose in cancer cells, and genes involved in central glucose metabolism (HK2, ENO1, PKM, and LDHA), PPP (G6PD), and de novo serine biosynthesis pathway (PSAT1, PSPH, and SHMT2)." (PMID 40371988, 2025). "Consequently, we selected five genes—INHBA, MMP7, PSAT1, SLC7A5, and TGFBI—to evaluate their mRNA expression levels in normal colon tissues compared to their corresponding cancer tissues." (PMID 39628390, 2024). "In addition, the lncRNA BC200 promotes the migration and invasion of cancer cells via the regulation of ATF4 expression, which in turn regulates the expression of PSAT1 in ESCC." (PMID 37147729, 2023). "The WGCNA on DEFs of paired NSCLCs revealed association of low tumour folate with increased transcripts of GLUT1/4, PHGDH, PSPH, and PSAT1 in NSCLCs, suggesting increased glucose uptake and enhanced glycolytic SSP pathways to contribute cancer serine levels under folate-deficit condition." (PMID 36615660, 2022). "YAP is also an activator of the glutamate-related aminotransferases glutamic-oxaloacetic transaminase 1 (GOT1) and phosphoserine aminotransferase 1 (PSAT1), which mediate the conversion of glutamate to α-ketoglutaric acid (α-KG), thereby stimulating cancer cell growth." (PMID 34765600, 2021). "PHGDH and the other enzymes in the serine synthesis pathway—phosphoserine aminotransferase 1 (PSAT1) and phosphoserine phosphatase (PSPH)—can also be activated in cancer cells by epigenetic mechanisms and by the transcription factor ATF4 downstream of both mTOR and Nrf2 signaling." (PMID 31096630, 2019). "From the seven most promising candidates, six (APC, CCND2, FOXA1, PSAT1, RASSF1A and SCGB3A1) confirmed its cancer-specificity, discriminating normal from cancerous tissues, although with variable performance, paralleling previous observations from our team and others." (PMID 30405052, 2018). "PSAT1, PHGDH, and SHMT2 are three key enzymes in the serine and glycine pathway and enhanced serine and glycine biosynthesis provides sufficient precursors for the synthesis of proteins, nucleic acids, and lipids for highly proliferating cancer cells." (PMID 28693523, 2017). "Their study suggested that serine production from the glycolytic intermediate mediated by PHGDH/PSAT1/PSPH pathway is unlike to be the reason of the cancer dependency of PHGDH in vitro." (PMID 24318446, 2013). "For example, PKCζ blocks SSP activation by suppressing PHGDH and PSAT1 activity, and PKCζ phosphorylates PHGDH at T57/T78 to inhibit its enzymatic activity, while PKCζ deletion restores the necessary metabolic processes mediated through the SSP in starved cancer cells." (PMID 36755301, 2023). "Moreover, tumor-related protein p73 (TRP73), hypoxia-inducible factor (HIF)-1, specificity protein 1, and nuclear transcription factor Y have been reported to induce the expression of PHGDH, PSAT1, and PSPH, which contribute to regulating serine biosynthesis and metabolism in cancer cells [,61]." (PMID 37187454, 2023).
cancer (continued). "Thirdly, while PSAT1 expression was found to be involved in immune cell infiltration of cancer, we could not demonstrate that PSAT1 affects patient survival through immune infiltration." (PMID 36105075, 2022). "PSAT1 expression is significantly correlated with the infiltrating of immune cells: B cells in 13 types of cancer, CD4+ T cells in 17 types of cancer, CD8+ T cells in 12 types of cancer, Neutrophil in 11 types of cancer, macrophages in 14 types of cancer and DCs in 13 types of cancer." (PMID 36105075, 2022). "Thus, in cancer cells, PARP1 and PSAT1 inhibition could fail to promote changing in gene expression leading to cell death." (PMID 31105872, 2019). "As NRF2 upregulate a series of detoxification genes and protect cancer cells against insults, our results demonstrated that the sensitivity of nedaplatin may be influenced by other NRF2 downstream genes, including but not limited to AKR1C3, GST, and PSAT1." (PMID 27601007, 2016). "The present study focused more on the non-metabolic regulatory functions of PSAT1 and performed GSEA pathway enrichment in pan-cancer." (PMID 40612679, 2025). "Given this heterogeneous expression profile, no research on PSAT1 has been reported in the MDS context, and the recent pieces of evidence of PSAT1 involvement in cancer motivated us to explore its impact in this study." (PMID 39186541, 2024). "Studies have shown that in the absence of amino acids, cancer cells induce the expression of PHGDH, PSAT1, and PSPH in a GCN2-ATF4-dependent manner to produce sufficient amino acids." (PMID 37147729, 2023). "Although PSAT1 is postulated to promote tumor growth through its enzymatic function within the serine synthesis pathway (SSP), its role in cancer progression has not been fully characterized." (PMID 34439090, 2021).
tumor (101 papers, 2006 to 2025). "Here, we report that in vitro-activated CAF-like cells promoted OS metastasis by reprogramming the metabolic profile of the tumor cells and increasing the levels of the serine metabolism-associated enzyme PSAT1." (PMID 40612679, 2025). "Consistent with the in vitro findings, xenograft tumors derived from HNRNPM-deficient cells also exhibited elevated PSAT1 levels, although tumor growth remained largely unaffected." (PMID 40784984, 2025). "Multivariate Cox regression analysis showed that age, tumor grade, neoadjuvant therapy, and PSAT1 level were significantly associated with patient prognosis." (PMID 38614981, 2024). "It has been shown that increased expression of MTHFD2 and PSAT1 is associated with enhanced metabolism and survival, and it is often evident in tumor ECs." (PMID 36766885, 2023). "Loss of LKB1 in mutant KRASG12D tumor cells modulates the expression of PSAT1 and PSPH in an mTOR-dependent manner." (PMID 37187454, 2023). "In general, high expression of PSAT1 not only promotes tumor metastasis, but also causes resistance to EGFR inhibitors, which together leads to poor prognosis in LUAD patients." (PMID 36699468, 2022). "We found the expression of PSAT1 is associated with immune cell infiltration in a number of tumor types, especially in BRCA and LUSC." (PMID 36105075, 2022). "Upregulation of the serine-glycine biosynthetic pathway due to overexpression of phosphoserine aminotransferase 1 (PSAT1) is associated with higher tumor proliferation and poorer prognosis in CRC and BC." (PMID 36618350, 2022). "Depending on the tumor type, several reports have implicated PSAT1 in many oncogenic processes including proliferation, migration, invasion, and chemo-resistance." (PMID 34439090, 2021). "An elevated expression of phosphoserine aminotransferase 1 (PSAT1) has been observed in multiple tumor types and is associated with poorer clinical outcomes." (PMID 34439090, 2021). "Lastly, the findings advocate that tumor stratification by co‐mutations to KRAS/NF1 highlights the LAUD patient population expected to be susceptible to inhibiting PSAT1." (PMID 31036704, 2019). "Lastly, the work suggests that tumor stratification by co‐mutations to KRAS/NF1 highlights the LAUD patient population expected to benefit from inhibiting PSAT1." (PMID 31036704, 2019). "The relative mRNA expression levels of PSAT1 were analyzed in 72 ER-negative breast tumors, and PSAT1 up-regulation was strongly associated with tumor size (P < 0.05) and axillary lymph node metastasis (P < 0.05)." (PMID 29216929, 2017). "Furthermore, silencing ITGA2 abrogates the promotion of tumor cell migration, invasion, and adhesion caused by PSAT1 overexpression." (PMID 39199378, 2024). "Furthermore, expression of PSAT1 was correlated with both tumor mutational burden (TMB) and microsatellite instability (MSI) in BRCA." (PMID 36105075, 2022). "In addition, the diagnostic ROC curve showed that the area under the curve of PSAT1 was 0.839, indicating that PSAT1 may be a promising tumor diagnostic marker for UCEC." (PMID 36906716, 2023). "In addition, we also performed bioinformatics analysis to determine the relationship between the expression of PSAT1 and promoter methylation, gene mutation, as well as tumor immune microenvironment and immunotherapy efficacy prediction in a variety of human tumors." (PMID 36105075, 2022). "In contrast, increased levels of expression of phosphoserine aminotransferase (encoded by PSAT1), which was another gene also identified in our myoepithelial transcriptome, was the strongest predictive marker for a poor response to tamoxifen therapy in ER-positive tumours." (PMID 17014703, 2006). "IHC analysis of tumor tissues revealed reduced PSAT1 and Ki67 expression and elevated c-caspase 3 levels following AURKB knockdown." (PMID 40784984, 2025).
tumor (continued). "The immunofluorescence results indicated that PSAT1 fluorescence in the metastatic tissues was consistent with the H&E-stained tumor areas, demonstrating high levels of PSAT1 in OS lung metastases." (PMID 40612679, 2025). "In vivo validation using xenograft models further confirmed that AURKB knockdown suppressed tumor growth, and this effect was significantly reversed by PSAT1 overexpression." (PMID 40784984, 2025). "H3K18la epigenetically activates AURKB transcription, and elevated AURKB subsequently disrupts HNRNPM-mediated PSAT1 mRNA degradation, stabilizing PSAT1 expression and promoting tumor growth." (PMID 40784984, 2025). "qPCR analysis revealed that CSAD, IL4I1, and P4HA3 were significantly upregulated in tumor specimens, whereas PSAT1 expression was notably reduced in ccRCC tissues (p<0.05)." (PMID 41584585, 2025). "Intriguingly, a recent study reported that PSAT1 depletion suppresses tumor growth only under exogenous serine deprivation, suggesting a compensatory role for nutrient uptake." (PMID 40784984, 2025). "report that in colon cancer models, combining the Ser Def diet (which restricts exogenous supply) with PSAT1 knockout (which blocks endogenous synthesis) results in greater tumor growth suppression in vitro and in vivo than that of either intervention alone." (PMID 41415540, 2025). "The high expression of PSAT1 in tumor tissues, especially late-stage tumor tissues, combined with clinical data, in this nomogram enhances its prognostic value in different-stage ccRCC patients, particularly for the prediction of OS." (PMID 38614981, 2024). "Immunohistochemical staining in serial sections also confirmed a positive correlation between the expression levels of PSAT1 in human ccRCC tumor tissues and the disease stage." (PMID 38614981, 2024). "Corroborating the establishment of immunological memory, animals that experienced tumor eradication were protected against a rechallenge with live PSAT1-defective CT26 cells while allowing for the development of mouse mammary carcinoma 4T1 lesions." (PMID 39206097, 2024). "The studies showed that PSAT1 plays the part of a crucial character in the regulation of tumor metastasis." (PMID 38706897, 2024). "Not only that, hub gene PSAT1 can also enhance immunosuppressive through PERK-ATF4-PSAT1 axis in tumor." (PMID 38648205, 2024). "To validate these observations, we conducted IHC staining on CRC tumor samples and adjacent paracancerous tissues, which further confirmed the decreased expression of PSAT1 in CRC tissues." (PMID 38706897, 2024). "PSAT1 is a member of the V-class pyridoxal phosphate ester-dependent transaminase family that fuels tumor cells by generating serine." (PMID 37534256, 2023). "In ESCC, the expression of miR-340 is negatively correlated with that of PSAT1 and significantly lower in tumor tissues than in paraneoplastic tissues." (PMID 37147729, 2023). "In EGF receptor–activated lung cancer, overexpression of PSAT1 contributes to tumor cell metastasis by promoting nuclear PKM2 translocation." (PMID 37187454, 2023). "Together, these data suggest that PSAT1 is critical for the nuclear translocation of PGC-1α and thus promotes the transcription of TFAM in tumor cells expressing the p5372P variant." (PMID 36788227, 2023). "In fact, several scholars have found a connection between PSAT1 and cell proliferation in some tumour cells." (PMID 36732787, 2023). "In NSCLC, the lncRNA MEG8 is expressed at higher levels in tumor tissues than in normal adjacent tissues and promotes tumor progression by regulating the miR-15a/b-5p/PSAT1 axis." (PMID 37147729, 2023). "And the expression levels of PSAT1 were also higher in the 23 tumor tissues compared to the paired normal tissues." (PMID 36906716, 2023). "Researchers have found that PSAT1 is aberrantly expressed in various tumor cells and promotes proliferation, metastasis, invasion, and drug resistance in a variety of malignancies, including breast, lung, and colorectal cancer." (PMID 36061202, 2022).